THY1 (Thy-1 cell surface antigen)
Diseases named in the same sentence as THY1 in open-access papers (continued):
Sharing a sentence is not in itself a finding about the gene and the disease.
tumor (continued). "Furthermore, we found that residual tumor cells in MTB;TetO-Wnt1;TTC;rYFP mice were enriched ~ 8-fold for CD24+Thy1+ tumor cells compared to primary tumors." (PMID 34088357, 2021). "Collectively, we identified that THY1 could be a critical biomarker in predicting ICI efficiency and a potential target for avoiding tumor immunotherapy resistance." (PMID 35071018, 2021). "Interestingly, a small proportion of these Thy1+ cells expressed MHC class II protein, confirming that cells with Cd74high CAF profile are also present in both tumor and normal mammary tissue." (PMID 32455670, 2020). "Expression of canonical markers of tumor fibroblasts, including Thy1, Fap, and Pdpn was indistinguishable from other CAF subsets, and ilCAFs also lacked transcripts for endothelial, hematopoietic, and epithelial cell linages, indicating a fibroblast nature." (PMID 33298926, 2020). "In contrast to CAFs, Thy-1+ LFs exhibit no myofibroblastic features or pro-invasive activity and secrete fewer cytokines in co-culture with tumor cells." (PMID 28744021, 2017). "Second, Thy-1 cell surface antigen (THY1 or CD90) is a membrane protein involved in the regulation of a variety of cell–cell interactions including immune system function, cell adhesion and tumour suppression." (PMID 27575253, 2016). "Interestingly, the proportion of different lymphocyte subpopulations was altered in tumors in which SK1 was inhibited, with a significant increase of NK cells as well as T-cells (Thy1+) such as CD4+ and CD8+ tumor-infiltrating lymphocytes." (PMID 27708249, 2016). "As an effort toward evaluating the therapeutic potential of some of endothelial targets in humans that we identified, we focused on B7H3, Thy-1 and ATP1B3, which were among the more differentially expressed cell surface tumor-specific endothelial markers identified by MS in this study." (PMID 24236063, 2013). "In our previous study, using the surface marker CD90 (Thy-1, expressed by hepatic stem/progenitor cells), liver CSCs were identified in HCC cell lines, tumor specimens and peripheral blood samples of HCC patients and these CD90+CSCs displayed tumorigenic capacity." (PMID 22606345, 2012). "However, in UCEC, dysregulation of COL1A1, ITGB1, THY1, and PDGFRA may compromise immune function, enabling tumor progression." (PMID 40817072, 2025). "As a member of the Thy-1/Ly-6 family involved in cell adhesion and metastasis, PSCA’s overexpression in high-grade PCa and metastatic lesions underscores the therapeutic potential of PSCA inhibitors in targeting tumor-stroma crosstalk to prevent metastatic spread." (PMID 41247789, 2025). "However, rare cells in our cultures, displaying both EpCAM and Thy-1, were multinuclear and thus appeared to be derived from tumor/stroma cell fusions rather than from EMT." (PMID 31181618, 2019). "Using our dataset and another high-quality dataset, we identified proteins that showed clinical prognosis and recurrence associations, of which GGACT, LXN, THY1, SYNPO2, ACMSD and COLEC11 were unique biomarkers identified from NAT that could not be revealed using tumor-based analysis." (PMID 37575948, 2023). "Interestingly, THY-1, Thrombomodulin, and Neprilysin, which were more highly enriched in hTERT-immortalized MSC EVs, may have potential roles in biological processes related to inflammation, tumor suppression, cellular differentiation and migration, regeneration, and apoptosis." (PMID 38786083, 2024). "Levels of CD90 (THY1), CD133 and EpCAM mRNA were measured in tumor tissues from 13 patients with DPHCC and 34 patients with non- DPHCC subtypes." (PMID 32231746, 2020). "In low tumor Hp expression group, TWIST1 (r = -0.54, p < 0.01), LAMB1 (r = -0.58, p < 0.001), and THY1 (r = -0.48, p < 0.01) showed negative correlation with Hp." (PMID 28158312, 2017). "Conversely, some genes (VSIG4, MFAP5, THY1, TSHZ2) showed little to no expression in tumor cells." (PMID 40954493, 2025).
tumor (continued). "Interestingly, the WISP-1 level was increased in culture medium of Thy1+ CAFs and in serum but not in culture medium of CD326+ tumor cells or CD11b+ TAMs isolated from primary tumors, indicating that the source of WISP-1 was CAFs in the TME." (PMID 36241874, 2022). "The established cell lines, with the expression of porcine SSC and germ cell markers UCHL1, PLZF, THY1, VASA and DAZL, could respond to retinoic acid (RA), and could colonize the recipient mouse testis without tumor formation after transplantation." (PMID 32308978, 2020). "As a quality check of the enriched population, we assessed that the isolated cells lacked expression of tumor (dsRED), immune (Ptprc) and endothelial markers (Pecam1) and expressed the mouse CAF-specific signature we previously identified (e.g. Rarres2, Fap, Lum, Thy1)." (PMID 38509063, 2024).
cancer (351 papers, 2006 to 2026). A tumor composed of atypical neoplastic, often pleomorphic cells that invade other tissues. "In hepatocellular and renal carcinomas, THY1 expression has been linked to cancer stem-like properties, enhanced invasiveness, and poor prognosis." (PMID 40476057, 2025). "The high expression of Thy-1 has been associated with several types of cancer; however, its impact on the prognosis of the disease appears to be context-dependent." (PMID 38254918, 2023). "In the context of hepatocellular and renal carcinomas, high expression of the THY1 gene has already been associated with poor prognosis and as a marker of cancer stem cells with tumorigenic and metastatic capacity." (PMID 38254918, 2023). "For the 20% elastin hydrogel, results showed that various biomarkers, including myofibroblast cell markers (α-SMA, THY-1) and cancer-associated markers (PDGF-β, S100A4), were involved in the FMT." (PMID 37848974, 2023). "The THY1 gene encodes the cell surface protein CD90 which has been demonstrated to be a marker for cancer stem cell populations in gastric and liver tumors." (PMID 22848499, 2012). "CD90 is one of the important markers in HCC, and it is Thymus cell antigen 1 (Thy-1), a stem cell antigen that plays an essential role as a marker for cancer stem cells (CSCs)." (PMID 41357196, 2025). "Thy-1 has also been proposed as a putative cancer stem cell (CSC) marker in hepatocellular carcinoma, GBM, and BC." (PMID 41463341, 2025). "THY1, also known as CD90, was highly upregulated in the squeezed group, a protein associated with calcium dependent integrin interactions between cancer cells and the endothelium." (PMID 40890143, 2025). "Our analysis revealed associations between the expression of COL1A1, ITGB1, THY1, and PDGFRA genes and different cancer stages in UCEC, however, the results were insignificant due to the lesser number of samples." (PMID 40817072, 2025). "THY1, a glycoprotein regulating cell-cell and cell-matrix interactions, is down-regulated in various cancers." (PMID 40817072, 2025). "Immune-related genes, such as COL1A1, ITGB1, THY1, and PDGFRA, have been implicated in various cancers, but their roles in UCEC remain underexplored." (PMID 40817072, 2025). "While αSMA and THY1 were abundant in cancer tissues, high abundance in normal tissues limited their targeting potential." (PMID 39335130, 2024). "Results from the PrognoScan and GEPIA consistently demonstrated that up-regulated THY1 significantly predicted poorer survival in many malignant tumors, including LUSC." (PMID 38819947, 2024). "We further used the ONCOMINE to explore the full landscape of THY1 expression in different malignant tumors compared to normal tissues." (PMID 38819947, 2024). "The analysis indicated that THY1 was significantly up-regulated and closely correlated with poor prognosis in many malignant tumors, including LUSC." (PMID 38819947, 2024). "We further used the GEPIA to measure the prognostic values of THY1 in 33 types of cancers from TCGA." (PMID 38819947, 2024). "Other markers, like CD248 (endosialin, also known as tumor endothelium marker 1, TEM1) and CD90/THY-1, are highly expressed by PCs but also by pMSCs, especially in the context of cancer." (PMID 37686315, 2023). "We also demonstrated that the low level of elastin concentration induced some cancer-associated fibroblast (CAF) markers, including PDGFR-β, and fibrosis-related disease markers, including THY-1." (PMID 37848974, 2023).
cancer (continued). "For cell–cell contacts, CD99, MPZ and THY1 were the common cellular interaction media in most cancers." (PMID 36772945, 2023). "In malignant pleural mesothelioma, Thy-1 is found overexpressed in primary cancer cells obtained from tumors exposed to chemotherapeutic drugs in vitro." (PMID 35733855, 2022). "Thy-1 displays strong physiological and pathological implications in development, cancer, immunity, and tissue fibrosis." (PMID 35733855, 2022). "The αvβ3 integrin–Thy-1 interaction mediates the binding of various cancer cells to endothelial cells (ECs)." (PMID 35733855, 2022). "First, we used a computer-based tool EPIC (Estimating the Proportion of Immune and Cancer cells) 22 to determine the correlation between THY1/CD90 expression and immune infiltration." (PMID 34987640, 2022). "To find a more targeted gene, we filtered these hub genes according to GS.TIDE, expression levels in cancer, and survival probability, and selected THY1 as the key gene in the pink module." (PMID 35071018, 2021). "Analysis of clinical samples showed a positive correlation between THY1 and classical cancer stemness marker SOX9." (PMID 35071018, 2021). "In cancer, Thy-1 has been proposed as a tumor suppressor, suggesting an overlapping role in both diseases." (PMID 34361103, 2021). "THY1 is an important protein in malignant tumors and is considered a candidate marker of CSCs with highly tumorigenic and metastatic potential due to its regulation of cell-cell interactions, cell-matrix interactions, cellular adhesion, and migration." (PMID 35071018, 2021). "Correlation analysis revealed that THY1 had a strong positive correlation with cancer stemness markers, as well as immunosuppressive markers and cells, especially with the TIDE score (Cor = 0.578, p = 4.293e-50)." (PMID 35071018, 2021). "In both cancer cell types, Thy-1 induced a rapid increase in intracellular Ca2+, ATP release, as well as cell migration and invasion." (PMID 33511115, 2020). "Instead, they express constellation of group-defining genes, including Ly6a, Cd34, and Thy1, which have been shown to mark other adult stem cells, such as HSCs, keratinocyte stem cells, cancer stem cells, muscle stem cells etc." (PMID 32286228, 2020). "Thymocyte differentiation antigen-1 (THY-1), also known as CD90 (Cluster of Differentiation 90), is a highly conserved glycoprotein that has been demonstrated to be a cancer biomarker." (PMID 32396525, 2020). "(ii) What is the molecular mechanism involved in cancer cell migration downstream of Thy-1-Integrin interaction?" (PMID 33511115, 2020). "Increasing evidence points toward the involvement of Thy-1 in the regulation of cancer cell progression and metastasis." (PMID 33511115, 2020). "THY1 is a glycophosphatidylinositol-anchored protein, which has been proposed to play important roles in cancers." (PMID 32867782, 2020). "The broader role of Thy-1 in cancer is complex, as it has been shown to both promote tumorigenesis and to function as a tumor suppressor; this conundrum has been recently reviewed." (PMID 30859102, 2019). "Is there a third protein regulating the conformational state of Thy-1/CD90-integrin interaction to induce such different effects in cancer cells?" (PMID 31428610, 2019). "A study in hepatocellular carcinoma cells showed that the presence of Thy-1, which is a cancer stem cell marker in these tumors, is correlated with enhanced Notch signaling." (PMID 30859102, 2019). "Accordingly, the functions of Thy-1 have been studied in a broad range of fields, including immunology, neurobiology, cancer, stem cell biology, tissue remodeling and aging, and have been the focus of multiple excellent reviews." (PMID 30859102, 2019). "Thy1: a cell-surface antigen, also known as CD90, mediates the cell adhesion, and communication of cancer stem cells." (PMID 31555586, 2019). "TFF1, THY1, and AKR1B10 are associated with various cancers and have been implicated as biomarker candidates." (PMID 29713252, 2018).
cancer (continued). "CD90 (also called THY1) was identified in the thymus as a T-cell differentiation and maturation marker, nevertheless human fibroblasts and cancer stromal cells also express abundant CD90 on their surface." (PMID 29029509, 2017). "CD90 (Thy-1) plays important roles in oncogenesis and shows potential as a candidate marker for cancer stem cells (CSCs) in various malignancies." (PMID 25536077, 2014). "In high-grade carcinomas a subset of cells adjacent to the stroma, demarked by the strong expression of Thy1, expresses either Thy1 or Sca1 or both markers." (PMID 20730114, 2010). "Despite these findings, the functional role of Thy-1 in cancer remains complex." (PMID 41463341, 2025). "Notably, hypermethylation of the CD90/Thy-1 promoter suppresses its expression, enhancing cancer cell invasiveness and fibrosis progression." (PMID 40625354, 2025). "Hence, we further measured the relationships between THY1 expression and immune cell infiltrates in 39 types of cancer from TCGA." (PMID 38819947, 2024). "Furthermore, we exprlored the expression of marker genes (PDPN, THY1, PDGFRB, PDGFRA,and POSTN) for cancer-associated fibroblasts (CAFs) in different cell types, and found that all marker genes were highly expressed in fibroblasts." (PMID 36973787, 2023). "Pro-fibrotic fibroblasts were transcriptionally similar to cancer associated fibroblasts and expressed high levels of collagens and periostin (POSTN), thymocyte differentiation antigen 1 (THY-1), and endothelin receptor A (EDNRA) predicted to be driven by a RUNX1 gene regulatory network." (PMID 36747878, 2023). "As can be seen, such a dual role of THY1 is cell context dependent and its interaction with different signaling molecules might explain the various functions in different cancers." (PMID 37046850, 2023). "THY1, SCG2, and RUNX1 play risk factors in various cancer types." (PMID 35498539, 2022). "Stromal cells (or cancer-associated cells) included endothelial cells (PECAM1/CD31+ and MMRN1+), fibroblasts (COL6A1+, COL1A1+, THY1+, and DCN+), epithelial cells (LAMC2+, KRT5+, and KRT14+), and unassigned name cells (high heat shock proteins expression), suggesting that they were cancerous cells." (PMID 35742914, 2022). "In addition, THY1 has been described as a marker of cancer stem cells (CSCs), and its up-regulation has been identified in different types of cancer." (PMID 35563422, 2022). "Similar to FAP, Thy‐1 cell surface antigen (THY1) is also overexpressed in prostate CAFs, and it may have a role in regulating cancer stem cells." (PMID 33600062, 2021). "Averaging these scores across cancer types/subtypes identified many ESGs that are strongly and consistently associated with the CAF signatures, including classical CAF markers such as FAP, SPARC, THY1 (CD90) and various collagens." (PMID 33972543, 2021). "The stroma is synthesized by cancer-associated fibroblasts (CAF); these cells are phenotypically different from normal fibroblasts and acquire markers such as alpha smooth muscle actin (αSMA), fibroblast activation protein (FAP), α1β1 integrin and Thy-1." (PMID 34361103, 2021). "However, the signaling pathway(s) triggered by this Thy-1-Integrin interaction in cancer cells remains to be defined." (PMID 33511115, 2020). "Thus, our results suggest that the Ca2+/hemichannel/ATP/P2X7 receptor-signaling axis triggered by the Thy-1-αVβ3 Integrin interaction is important for cancer cell migration, invasion and transvasation." (PMID 33511115, 2020). "Our secondary objective was to evaluate whether we could target Thy-1 to negatively impact cancer cell growth." (PMID 31735168, 2019). "Also biomarkers targeting stromal components and microenvironment such as uPAR and Thy1 are suggested for molecular imaging of cancer." (PMID 28915633, 2017). "THY1(CD90) is one of the representative HCC Cancer Stem Cells (CSCs) markers." (PMID 28158312, 2017). "A recent study identified THY1 (CD90) as a potential cancer stem cell marker in NSCLC." (PMID 27513329, 2016).